LINC01237 (long independently transcribed non-coding RNA 1237)
Synonyms: LINC01238
Gene: Long non-coding RNA gene on chromosome 2 (241,881,353 to 242,078,722, forward strand). Ensembl gene ENSG00000233806.
Diseases named in the same sentence as LINC01237 in open-access papers:
LINC01237 is named in the same sentence as 1 disease in open-access papers, as found by Europe PMC text mining. Sharing a sentence is not in itself a finding about the gene and the disease. The quoted sentences say what the papers report.
cancer (1 paper, 2020). A tumor composed of atypical neoplastic, often pleomorphic cells that invade other tissues. "The intersection set of the two gene lists includes 5 lncRNAs (EIF1AX-AS1, LINC00115, LINC01237, MALAT1 and LINC00528), among which only LINC00115 and MALAT1 have been experimentally validated to correlate with cancers according to the lncRNADisease2.0 database." (PMID 33318305, 2020).